TNF (tumor necrosis factor)
Diseases named in the same sentence as TNF in open-access papers (continued):
Sharing a sentence is not in itself a finding about the gene and the disease.
rheumatoid arthritis (continued). "Recently, specific radiolabeled mAb including anti-CD20 and anti-TNF-α have been introduced for imaging of chronic inflammatory autoimmune joint diseases such as rheumatoid arthritis." (PMID 26566952, 2015). "Clinical studies have shown that subsets of patients with rheumatoid arthritis (RA) develop anti-drug antibodies towards anti-TNFα biologics." (PMID 26270649, 2015). "Rheumatoid arthritis patients, as well as children with chronic arthritis being treated with TNF-α antagonists can develop lupus-like symptoms due to overexpression of IFN-α and ISGs." (PMID 26709698, 2015). "Effects of inflammatory factors, such as IFN-γ and TNF-α, in rheumatoid arthritis have also been proven to negatively influence the osteogenic differentiation of MSCs and to induce their apoptosis." (PMID 25999667, 2015). "The purpose of the present study was to investigate the relationship involving these autoreactive T cells, the rheumatoid arthritis immunopathology, and the response to tumor necrosis factor-α inhibitor therapy." (PMID 26061065, 2015). "Patients with inflammatory rheumatisms, such as rheumatoid arthritis, are more prone to develop skin cancers than the general population, with an additional increased incidence when receiving TNF blockers." (PMID 25996152, 2015). "For example, EGCG was reported to sensitize HUVEC to ischemia/reperfusion, rheumatoid arthritis synovial fibroblasts to tumor necrosis factor α, and CD4+ T cells to interferon γ." (PMID 26375285, 2015). "The introduction of tumor necrosis factor (TNF) blocking agents into the therapy of rheumatoid arthritis (RA) is a story of remarkable success." (PMID 26107717, 2015). "Majority (67.6%) of our Rheumatoid Arthritis patients had active disease and would have high inflammatory cytokines like TNF and IL-6 which is also contributing to depression." (PMID 26101498, 2015). "It has been demonstrated in transgenic mice, bearing human-TNFα to resemble a rheumatoid arthritis model, that mTOR signaling drives OC function, and that inhibition of this pathway can mitigate bone erosion." (PMID 26468083, 2015). "The aim of this study was to assess long-term golimumab therapy in rheumatoid arthritis (RA) patients who discontinued previous tumor necrosis factor-α (TNF)-inhibitor(s)." (PMID 25627338, 2015). "Advances in the treatment of rheumatoid arthritis (RA) including anti-tumor necrosis factor (anti-TNF) monoclonal antibodies have led to successful control of the disease in many patients." (PMID 25885039, 2015). "Significant examples are the elevated production of IFN-γ, IL-6 and IL-17 consequent to an estrogen deficit in menopausal osteoporosis or the action of TNF-α in secondary osteoporosis due to rheumatoid arthritis." (PMID 26449657, 2015). "Several studies have implicated the role of TNF-α, IL-1β, IL-6 in the pathogenesis of a number of inflammatory diseases, such as inflammatory bowel disease (IBD), rheumatoid arthritis, sepsis and mucositis." (PMID 26618095, 2015). "Among these mediators, interleukin (IL)-6 and tumor necrosis factor-α (TNF-α) are representative pro-inflammatory cytokines, and their overproduction exacerbate various inflammatory states, including sepsis and rheumatoid arthritis." (PMID 25871292, 2015). "The aim of this study was to describe a clinical case of a patient with Alzheimer's disease (AD) in use of an anti-TNF-α agent for rheumatoid arthritis (RA)." (PMID 29213962, 2015). "On the other hand, the treatment with anti-TNF-α improves vascular endothelial function and decreases arterial stiffness in postmenopausal women and rheumatoid arthritis patients." (PMID 26504819, 2015). "Since pro-inflammatory mediators as tumor necrosis factor-α (TNFα) or Interleukin-1β (IL1β) are elevated in rheumatoid arthritis patients and trigger atherogenesis, the design of new drugs is focusing on the reduction of these inflammatory mediators." (PMID 26076475, 2015).
rheumatoid arthritis (continued). "For instance, TNF-targeting treatments in Crohn’s disease, rheumatoid arthritis or psoriasis, which lead to significant improvements, illustrate the dark side of TNF." (PMID 26071594, 2015). "Biologic drugs, such as the anti–tumor necrosis factor (anti‐TNF) antibody adalimumab, have represented a breakthrough in the treatment of rheumatoid arthritis." (PMID 26097196, 2015). "In the synovial fibroblasts of patients with rheumatoid arthritis, IL-33 was detected and was markedly upregulated by the addition of TNF-α and IL-1β." (PMID 26557152, 2015). "In recent years, the treatment of rheumatoid arthritis (RA) has rapidly advanced, and many biologic drugs, including tumor necrosis factor (TNF) inhibitors, are now available." (PMID 25417119, 2014). "Anti-TNF is effective for the treatment of rheumatoid arthritis, seronegative spondyloarthropathy, and inflammatory bowel disease." (PMID 25047809, 2014). "Two months of etanercept treatment, used at the same treatment regimen as that used in humans with rheumatoid arthritis, led to a significant decrease in TNFα in β2KO mice when compared to untreated β2KO mice." (PMID 25138272, 2014). "In phase III trials for rheumatoid arthritis, tofacitinib was efficacious in patients with inadequate responses to tumor necrosis factor inhibitors, methotrexate monotherapy, or disease-modifying antirheumatic drugs." (PMID 24883332, 2014). "In this mouse model, IL-36α enhances the production of pro-inflammatory cytokines IL-17A, IL-23p19 and TNF-α in skin inflammation, cytokines which are also involved in rheumatoid arthritis." (PMID 25111378, 2014). "TNFα antagonists are a significant advantage for the treatment of rheumatoid arthritis (RA), spondyloarthropathies (SpA), and other inflammatory diseases." (PMID 24938855, 2014). "The recognition that cytokines are major players in rheumatoid arthritis (RA) has led to powerful disease-modifying therapies which are based on the neutralization of proinflammatory cytokines such as TNF." (PMID 25606597, 2014). "Caspase-1 expression in rheumatoid arthritis (RA) synovial fibroblasts treated with TNF was assessed by qRT-PCR and Western blot." (PMID 24762050, 2014). "Tumor necrosis factor-alpha (TNF-alpha) inhibitors have been used in a wide range of inflammatory diseases (e.g., rheumatoid arthritis, psoriasis, and inflammatory bowel disease)." (PMID 25389506, 2014). "Tumor necrosis factor α (TNF α) inhibitors are commonly used for treatment of aggressive rheumatoid arthritis and other rheumatic diseases." (PMID 24949211, 2014). "Rheumatoid arthritis (RA) is a chronic inflammatory disease in which pro-inflammatory cytokines, including tumor necrosis factor (TNF)-α, play a crucial role." (PMID 25988122, 2014). "Of note, TNFα neutralization was reported to improve insulin resistance in diabetic patients with rheumatoid arthritis or Crohn's disease who were also receiving anti-TNFα treatment (infliximab) for their autoimmune disease." (PMID 24203314, 2014). "Novel molecules that specifically target human TNFα in rheumatoid arthritis pose problems for preclinical assessment of efficacy." (PMID 25344414, 2014). "The study cohort included rheumatoid arthritis patients who initiated the first course of a TNF antagonist between 2001 and 2008." (PMID 25141123, 2014). "TNF-α is a potent pro-inflammatory cytokine with elevated levels found in several autoimmune diseases including rheumatoid arthritis and CD." (PMID 24728142, 2014). "The hTNFtg mouse is a commonly used model for rheumatoid arthritis which develops clinical symptoms of arthritis spontaneously at 5 to 6 weeks after birth by constitutively expressing the human TNF gene." (PMID 25111378, 2014). "Recent studies have shown that treatment with anti-TNF agents modifies cardiovascular burden in patients with rheumatoid arthritis via an increase in HDL and total cholesterol." (PMID 24587984, 2014).
rheumatoid arthritis (continued). "As in other rheumatic conditions, such as rheumatoid arthritis (RA), a switch to another TNF-α antagonist, due to ineffectiveness or occurrence of adverse events, can often restore therapeutic response." (PMID 25110401, 2014). "CERTAIN will inform effectiveness and safety questions to compare anti-TNF to non anti-TNF biologic agents for the treatment of rheumatoid arthritis." (PMID 24690143, 2014). "TNF-blocking biologic agents were introduced into the therapy of rheumatoid arthritis and other autoimmune and inflammatory diseases in the late 1990s." (PMID 24620738, 2014). "Infliximab is a chimeric monoclonal anti-TNF antibody used to treat several inflammatory diseases, namely, the spondyloarthropathies (ankylosing spondylitis and psoriatic arthritis), rheumatoid arthritis, and inflammatory bowel disease." (PMID 25436167, 2014). "Tumor necrosis factor (TNF) and, possibly, lymphotoxin alpha (LTα) signaling contribute to inflammation and rheumatoid arthritis (RA) pathogenesis." (PMID 25359150, 2014). "Previous reports have showed that artesunate can decrease the secretion of proinflammatory cytokines from TNF-α-stimulated human rheumatoid arthritis fibroblast-like synoviocytes." (PMID 25116436, 2014). "In the late 1980’s, experiments in human synovial tissue explants identified tumor necrosis factor (TNF) as an important cytokine in the pathogenesis of rheumatoid arthritis (RA)." (PMID 24839407, 2014). "Further studies on fracture healing under chronic inflammatory conditions in animal models and rheumatoid arthritis patients will be necessary to further elucidate the mechanisms of this positive effect of anti-TNFα-treatment." (PMID 24885217, 2014). "The first TNF-antagonists against inflammatory diseases were infliximab (first approved for the therapy of Crohn’s disease) and etanercept (first approved for rheumatoid arthritis), both of them receiving marketing authorization in 1998." (PMID 24620738, 2014). "Approximately 30% of rheumatoid arthritis patients achieve inadequate response to anti-TNF biologics." (PMID 25504080, 2014). "As in rheumatoid arthritis, switching to another anti-TNF-α agent can be an effective option when, during the treatment of AS or PsA, therapy is suspended because of inefficacy or an adverse event." (PMID 25110401, 2014). "In chronic inflammatory diseases, such as rheumatoid arthritis, overexpression of the pro-inflammatory cytokine tumor necrosis factor α (TNF-α) is thought to play an important role in disease progression." (PMID 25423092, 2014). "A direct comparison between conventional DMARD combinations with MTX plus anti-TNF was needed, and such a comparison was made in both the Swedish Farmacotherapy (Swefot) and the Treatment of Early Aggressive Rheumatoid Arthritis (TEAR) clinical trials." (PMID 24502187, 2014). "The data was consistent with the reported paper that anti-TNFα therapy in patients with rheumatoid arthritis decreases Th17 cell populations." (PMID 25436214, 2014). "Standard treatments for RP include immunosuppressive agents such as corticosteroids, biological agents such as tumor necrosis factor-α (TNF-α) inhibitors and anti-inflammatory agents commonly used to treat rheumatoid arthritis." (PMID 24576098, 2014). "This protective/modulatory effect of sTWEAK on TNFα activity has been observed in such pathologies as rheumatoid arthritis, ischemic stroke and several tumour epithelial cell lines, suggesting general competitive behaviour between sTWEAK and TNFα." (PMID 24565471, 2014). "Our group previously reported antibody response after seasonal influenza vaccine in rheumatoid arthritis patients (RA) treated with methotrexate (MTX) or anti-TNF remedies being as good as that of healthy controls." (PMID 24383620, 2014). "TNF-α-induced Treg cell dysfunction is correlated with increased numbers of Th1 and Th17 cells within the inflamed synovium in rheumatoid arthritis." (PMID 25133199, 2014).
rheumatoid arthritis (continued). "Many therapies are now available for patients with rheumatoid arthritis (RA) who have an inadequate response to methotrexate including tumor necrosis factor inhibitors, abatacept, tocilizumab, and rituximab." (PMID 24523570, 2014). "The IL-32-induced TNF production plays a role in inflammatory diseases such as inflammatory bowel disease and rheumatoid arthritis." (PMID 24884781, 2014). "Tumour necrosis factor α inhibitors (anti-TNF) have improved the treatment of rheumatoid arthritis (RA); however, the effect varies and approximately one third of patients do not respond." (PMID 24967817, 2014). "Tumor necrosis factor alpha (TNF-α) is one of the main trigger of chronic inflammation in rheumatoid arthritis." (PMID 24885217, 2014). "Anti-TNF biologics are an important class of therapeutics in the treatment of rheumatoid arthritis, but unfortunately approximately 30% of patients achieve inadequate response." (PMID 25504080, 2014). "This is notably highlighted by the use of anti-TNFα kinoid in a phase-2 trial in rheumatoid arthritis (ClinicalTrials.gov identifier NCT01040715) and Crohn’s disease (ClinicalTrials.gov identifier NCT01291810)." (PMID 25059342, 2014). "We report a case of Salmonella septic arthritis detected by ultrasound in a 40-year-old man with rheumatoid arthritis while he was on anti–tumor necrosis factor-α monoclonal antibody certolizumab." (PMID 26425605, 2014). "In studies using rheumatoid arthritis model, TQ was reported to reduce the serum levels of IL-1 and TNF-α." (PMID 24422662, 2014). "It has been implicated in the pathology of many autoimmune diseases and anti-TNF therapies are successfully used to treat autoimmune diseases such as rheumatoid arthritis, Crohn's disease and psoriasis." (PMID 24587232, 2014). "The features of CAIA in Tg1278TNFko animals make the model well-suited to testing the next generation of therapeutics that will target human TNFα in rheumatoid arthritis." (PMID 25344414, 2014). "TNFα plays an important role in autoimmune pathogenesis and is the main therapeutic target of rheumatoid arthritis." (PMID 25436214, 2014). "In a retrospective analysis of patients with rheumatoid arthritis on anti-TNF treatment the number of PHN after herpes zoster was remarkably lower (only two cases out of 206) compared to data of the general population." (PMID 25127283, 2014). "Elevated TNFα is a commonfeature in a range of inflammatory disorders and is detrimental to musclefunction in diseases such as rheumatoid arthritis and chronic obstructivepulmonary disease." (PMID 24413279, 2014). "Our results provide indication that rheumatoid arthritis patients, who sustained a fracture during the treatment with TNF-α antagonist, should continue this therapy." (PMID 24885217, 2014). "MCP-1 expression has already been detected at sites of tooth eruption, bone metastasis and Rheumatoid Arthritis, being regulated by inflammatory cytokines such as TNF-α and Interleukin (IL)-1b and hormones, such as PTH." (PMID 25229495, 2014). "Herewith, we describe the case of a great vessels arteritis in a patient affected by rheumatoid arthritis in therapy with an anti-TNF agent (etanercept)." (PMID 25544845, 2014). "Low MTX doses are able to reduce some important cytokines as TNFα that are elevated in autoimmune diseases such as rheumatoid arthritis." (PMID 25330300, 2014). "This is an interesting finding because monocytes are known to be the main producers of TNFα in innate immune responses and in chronic inflammatory diseases such as rheumatoid arthritis but little is known about the effects of TNFα on monocytes themselves." (PMID 24098349, 2013). "It has been reported that IL-15 is produced excessively in the joints of rheumatoid arthritis (RA) patients and induces recruitment of T cells to arthritic joints and activates T cells to induce tumor necrosis factor (TNF)-α production." (PMID 24366113, 2013).
rheumatoid arthritis (continued). "Several studies have measured high amounts of TNF-α in the serum and synovial fluid of patients with rheumatoid arthritis and psoriatic arthritis and children with juvenile idiopathic arthritis." (PMID 23762085, 2013). "More recently, it was reported that PGRN binds directly to TNF receptors and suppresses TNF-α-mediated inflammation in a mouse model of rheumatoid arthritis." (PMID 23972823, 2013). "Although the role of TNF-α in a wide variety of diseases, including rheumatoid arthritis (RA), is very well-documented, very little is known about TNF-β." (PMID 24283517, 2013). "In rheumatoid arthritis, TNF-α, IL-1, IL-6, and IL-17 produced by synovial macrophages and T cells act on osteoblasts to promote RANKL expression." (PMID 23762085, 2013). "TNF-α is the key mediator of joint inflammation and bone destruction in inflammatory arthritis, such as rheumatoid arthritis, psoriatic patients with arthritis, and juvenile idiopathic arthritis." (PMID 23762085, 2013). "Half of the selected studies evaluated abatacept in the treatment of rheumatoid arthritis, after failure of or intolerance to tumor necrosis factor alpha inhibitors." (PMID 23819062, 2013). "TNF-α-induced Treg cell dysfunction correlated with increased numbers of Th1 and Th17 cells within the inflamed synovium in rheumatoid arthritis." (PMID 24058613, 2013). "We determined the characteristic features of synovial tissues of rheumatoid arthritis (RA) patients treated by TNF inhibitors in order to delineate their mechanism of action." (PMID 23575549, 2013). "IL-6, LPS, IL-1β, IFN-α, IFN-γ and TNF-α induce CCAAT/enhancer-binding protein D (CEBPD) expression in rheumatoid arthritis." (PMID 23725043, 2013). "Treatment strategies blocking tumor necrosis factor (anti-TNF) have proven very successful in patients with rheumatoid arthritis (RA), showing beneficial effects in approximately 50-60% of the patients." (PMID 24040234, 2013). "TNF-α blockers, such as infliximab, adalimumab, certolizumab pegol, golimumab, and etanercept, have been approved for the treatment of rheumatoid arthritis and other immune-mediated diseases." (PMID 24373231, 2013). "In total 21 studies on the cost effectiveness of abatacept in the treatment of rheumatoid arthritis after failure of or intolerance to TNF-a inhibitors were identified." (PMID 23819062, 2013). "Recently, anti-TNF-α has been widely used in patients with rheumatoid arthritis, psoriatic arthritis, ulcerative colitis, Crohn's disease, and ankylosing spondylitis." (PMID 25374717, 2013). "As a consequence of the inflammatory action of TNFα, its overexpression in vivo, as in the case in transgenic mice, leads to inflammation resembling human rheumatoid arthritis with significant focal and systemic bone erosions." (PMID 24278766, 2013). "Tumor necrosis factor-α (TNF-α) inhibitors such as infliximab are used in treatment of various diseases like rheumatoid arthritis, Crohn's disease, ankylosing spondylitis, and psoriasis." (PMID 23762724, 2013). "Thalidomide, recently introduced into the treatment of rheumatoid arthritis and lupus, is responsible for angiogenesis and TNF-α inhibition." (PMID 23725043, 2013). "Tumor necrosis factor (TNF) plays an important role in the development of inflammatory diseases like rheumatoid arthritis, Crohn’s disease and the relapsing phases of multiple sclerosis." (PMID 23977237, 2013). "Tumor necrosis factor-alpha (TNFα) antagonism is an important treatment strategy in patients with rheumatoid arthritis, psoriatic arthritis, vasculitis, and ankylosing spondylitis." (PMID 23970991, 2013). "Two patients suffered from rheumatoid arthritis which was being treated with immunosuppressives, cortisone and with a TNF alpha blocker (Etanercept or Adalimumab)." (PMID 24066659, 2013).